BAZ2A (bromodomain adjacent to zinc finger domain 2A)
Description:
Regulatory subunit of the ATP-dependent NoRC-1 and NoRC-5 ISWI chromatin remodeling complexes, which form ordered nucleosome arrays on chromatin and facilitate access to DNA during DNA-templated processes such as DNA replication, transcription, and repair. Both complexes regulate the spacing of nucleosomes along the chromatin and have the ability to slide mononucleosomes to the center of a DNA template. Directly stimulates the ATPase activity of SMARCA5 in the NoRC-5 ISWI chromatin remodeling complex. The NoRC-1 ISWI chromatin remodeling complex has a lower ATP hydrolysis rate than the NoRC-5 ISWI chromatin remodeling complex. Within the NoRC-5 ISWI chromatin remodeling complex, mediates silencing of a fraction of rDNA by recruiting histone-modifying enzymes and DNA methyltransferases, leading to heterochromatin formation and transcriptional silencing (By similarity). In the complex, it plays a central role by being recruited to rDNA and by targeting chromatin modifying enzymes such as HDAC1, leading to repress RNA polymerase I transcription (By similarity). Recruited to rDNA via its interaction with TTF1 and its ability to recognize and bind histone H4 acetylated on 'Lys-16' (H4K16ac), leading to deacetylation of H4K5ac, H4K8ac, H4K12ac but not H4K16ac (By similarity). Specifically binds pRNAs, 150-250 nucleotide RNAs that are complementary in sequence to the rDNA promoter; pRNA-binding is required for heterochromatin formation and rDNA silencing (By similarity).
Synonyms: Tip5; KIAA0314; WALp3
Tractability: Small molecule: a structure with a bound ligand is known; a high-quality ligand is known. PROTAC: UniProt records ubiquitination sites on it; ubiquitination databases record sites on it; its protein half-life has been measured; a small molecule that binds it is known.
Target class: Epigenetic regulator; Bromodomain; Reader
Chemical probes: BAZ2-ICR (high quality), GSK2801 (high quality)
Gene: Protein-coding gene on chromosome 12 (56,595,596 to 56,636,913, reverse strand). Ensembl gene ENSG00000076108.
Subcellular location: Nucleus, nucleolus
Subcellular location (Human Protein Atlas): Nuclear speckles
Pathways (Reactome):
Gene expression (Transcription): NoRC negatively regulates rRNA expression
Gene Ontology:
Molecular function: histone binding; protein binding; RNA polymerase I core promoter sequence-specific DNA binding; histone H4K16ac reader activity; nuclear receptor binding; RNA binding; DNA binding
Biological process: chromatin remodeling; DNA-templated transcription; rDNA heterochromatin formation; regulation of DNA-templated transcription; RNA polymerase I preinitiation complex assembly
Cellular component: nuclear speck; nucleus; chromatin silencing complex; nucleolus; rDNA heterochromatin; nucleoplasm
Genetic constraint (gnomAD): Loss-of-function variants: 34 observed, 199.87 expected, observed/expected ratio (o/e) 0.17, 90% interval 0.13 to 0.23. The upper end of that interval is the gene's LOEUF score, 0.23, which puts it in group 1 of 6, group 1 being the genes least tolerant of losing a copy. Missense variants: 2,002 observed, 2,469.5 expected, observed/expected ratio (o/e) 0.81, 90% interval 0.78 to 0.84. Synonymous variants: 857 observed, 917.34 expected, observed/expected ratio (o/e) 0.93, 90% interval 0.88 to 0.99.
Homologues: Orthologues: chimpanzee BAZ2A (99% identical), macaque BAZ2A (98% identical), pig BAZ2A (91% identical), rabbit BAZ2A (87% identical), mouse Baz2a (84% identical), guinea pig BAZ2A (83% identical), rat Baz2a (83% identical), tropical clawed frog baz2a (44% identical), zebrafish baz2a (40% identical), Caenorhabditis elegans baz-2 (15% identical), Drosophila melanogaster Acf (13% identical). Paralogues in human: BAZ2B (33% identical), BAZ1A (15% identical), BPTF (13% identical), BAZ1B (13% identical), BRD4 (7% identical), KAT2B (6% identical), CECR2 (6% identical), BRD2 (6% identical), KAT2A (6% identical), BRD3 (5% identical), BRDT (5% identical).
Diseases named in the same sentence as BAZ2A in open-access papers:
BAZ2A is named in the same sentence as 40 diseases in open-access papers, as found by Europe PMC text mining. Sharing a sentence is not in itself a finding about the gene and the disease. The quoted sentences say what the papers report.
prostate carcinoma (16 papers, 2015 to 2026). A carcinoma that arises from epithelial cells of the prostate gland. "In human triple-negative breast cancer, inhibition of BAZ2A has been demonstrated to induce apoptosis, while BAZ2A has also been implicated in regulating hypermethylation, contributing to advanced tumor stages and recurrence in prostate cancer." (PMID 38951817, 2024). "The BAZ2A genomic population in prostate cancer cells correlates with the H3K14ac chromatin region; this BAZ2A/H3K14ac association is facilitated by BAZ2A-bromodomain (BAZ2A-BRD) via binding with H3K14ac." (PMID 36969009, 2023). "The levels of BAZ2A are upregulated and associated with poor prognosis and recurrence in various tumors, such as prostate cancer." (PMID 34736517, 2021). "Mechanismly, BAZ2A binds to a class of inactive enhancers that are marked by H3K14ac via its bromodomain and represses the expression of genes implicated in aggressive and dedifferentiated prostate cancer." (PMID 34736517, 2021). "BAZ2A is a large multidomain protein overexpressed in aggressive prostate cancer, where it potentiates migration and invasion of other tissues." (PMID 42233460, 2026). "In prostate cancer, the bromodomain of BAZ2A binds H3K14ac-enriched chromatin at inactive enhancers, repressing transcription of genes silenced in aggressive cancers." (PMID 41283357, 2025). "Previous studies have shown that BAZ2A is an epigenetic regulator involved in ribosomal RNA transcription and is overexpressed in prostate cancer and is a marker for predicting prostate cancer recurrence." (PMID 37925811, 2024). "In prostate cancer, BAZ2A (TIP5) was found overexpressed and interacting with EZH2 to maintain silenced anti-metastatic genes." (PMID 37369946, 2023). "Recent research has found that the bromodomain adjacent to zinc finger domain 2A (BAZ2A) is required for prostate cancer cells to acquire features similar to stem cells." (PMID 36969009, 2023). "BAZ2A represses rRNA genes (rDNA) that are transcribed by RNA polymerase I. In prostate cancer (PCa), BAZ2A function goes beyond this role because it represses genes frequently silenced in metastatic disease." (PMID 37184661, 2023). "The BAZ2A-TAM domain, in association with RNA, promotes the interaction with TOP2A and KDM1A that serves to repress genes critical to prostate cancer progression." (PMID 37184661, 2023). "Previously, BAZ2A has been reported to be a predictor of prostate cancer recurrence and a participator in hepatocellular cancer, indicating the oncogenic role of BAZ2A in cancers." (PMID 35012615, 2022). "Bromodomain Adjacent To Zinc Finger Domain 2A (BAZ2A) (TIP5) is overexpressed in prostate cancer, which is closely related to a molecular subtype displaying a CpG island methylator phenotype (CIMP)." (PMID 35281845, 2022). "BAZ2A are up-regulated in multiple tumors, such as prostate cancer, HCC, and chronic lymphocytic leukaemia (CLL)." (PMID 34736517, 2021). "Experiments inducing the up- and down-regulation of BAZ2A demonstrate that its up-regulation contributes to proliferation, viability, and metastatic potential of human prostate cancer cell lines." (PMID 28587163, 2017). "BAZ2A was found overexpressed in prostate cancer (PCa) cells and correlated with the tumor stage." (PMID 37574751, 2023). "BAZ2A-mediated repression in prostate cancer is regulated by the RNA-binding TAM domain." (PMID 37184661, 2023). "Additionally, BAZ2A has been shown by several studies to predict recurrence of prostate cancer and regulate hepatocellular cancer." (PMID 35012615, 2022). "The ISWI subunit BAZ1A was recently discovered as a regulator of cellular senescence, and the related BAZ2A subunit is also known to be overexpressed in prostate cancer, where it may be involved in prostate cancer metastatic regulation." (PMID 34298819, 2021). "Interestingly, high levels of BAZ2A correlate with the deletion of the PTEN gene in primary prostate cancer, which can be an indicator of poor prognosis." (PMID 34736517, 2021).
prostate carcinoma (continued). "BAZ2A is up-regulated in prostate cancer and is a useful marker for metastatic potential." (PMID 28587163, 2017). "The remodeling complex NoRC was shown to be involved in Ras dependent tumors and overexpression of miRNAs, regulating the expression of BAZ2A, result in progression to metastasis in prostate cancer and may also play a role in chronic lymphocytic leukemia." (PMID 26075616, 2015). "Furthermore, we determined that RNA-mediated interactions between BAZ2A and TOP2A and KDM1A repress genes critical to PCa and may prove to be useful to stratify prostate cancer risk and treatment in patients." (PMID 37184661, 2023). "Baz2A (non-catalytic subunit of NoRC complex) is a key epigenetic regulator linking aberrant DNA methylation and outcome in prostate cancer." (PMID 26075616, 2015).
hepatocellular carcinoma (5 papers, 2022 to 2024). A malignant tumor that arises from hepatocytes. "To explore its mechanism of action, we examined the transcriptome and proteome associated with BAZ2A in hepatoma cells." (PMID 38433277, 2024). "We examined several hepatoma cell lines and found that that BAZ2A transcription levels were highest in LM6 cells." (PMID 38433277, 2024). "The results of our functional experiments in hepatoma cells further substantiate the function of BAZ2A in facilitating cancer cell proliferation." (PMID 38433277, 2024). "In addition, BAZ2A can have a regulatory role in hepatocellular carcinoma, cervical cancer, and chronic lymphoblastic leukemia." (PMID 36292752, 2022). "Also, BAZ2A enhanced the tumorigenicity of hepatocellular carcinoma." (PMID 36674511, 2023).
cervical cancer (3 papers, 2022 to 2024). A primary or metastatic malignant neoplasm involving the cervix. "We also analyzed the transcriptome and metabolome of BAZ2A in other tumors, such as cervical cancer." (PMID 38433277, 2024). "However, the function of BAZ2A in cervical cancer and its correlation with LINC00885 or miR-3150b-3p have not been explored yet." (PMID 35012615, 2022).
colon cancer (3 papers, 2024). "We observed that several of the phenotypic and molecular changes associated with BAZ1A interference were recapitulated for BAZ2A in colon cancer cells." (PMID 39112459, 2024).
acute lymphoblastic leukemia (2 papers, 2009 to 2021). Leukemia with an acute onset, characterized by the presence of lymphoblasts in the bone marrow and the peripheral blood. "Moreover, a fusion of ETV6 with the BAZ2A intron sequence generated by a cytogenetically cryptic rearrangement between 12p13 and 12q13 occurred in a pediatric case of pre-B acute lymphoblastic leukemia (ALL), which encodes a truncated form of ETV6 that leads to a pathogenic effect." (PMID 34736517, 2021). "Interestingly, putative BAZ2A deregulation has been implicated in a paediatric case of pre-B acute lymphoblastic leukemia (ALL) in which a cryptic rearrangement between 12p13 and 12q13 generated a fusion of ETV with an intronic sequence of BAZ2A." (PMID 19779621, 2009).
breast carcinoma (2 papers, 2013 to 2024). "The genes containing the most significant SNPs for breast cancer ranged widely in apparent function with GWAS associations reported with SNPs in CFB (complement factor B) for age-related macular degeneration, BAZ2A for platelet counts and ACADS for metabolic traits." (PMID 23555315, 2013).
metastatic disease (2 papers, 2023 to 2024). "BAZ2A is highly expressed in metastatic tumors and promotes tumor cell proliferation and migration." (PMID 37925811, 2024). "Moreover, the repression of BAZ2A-TAM-dependent genes correlates with primary and metastatic tumours with high BAZ2A, KDM1A, and TOP2A content." (PMID 37184661, 2023).
ovarian carcinoma (2 papers, 2024). A malignant neoplasm originating from the surface ovarian epithelium. "Moreover, PCDH8, a protein coding that acts as a cell adhesion molecule, and BAZ2A having DNA binding activity, were suggested as missense novel genes in ovarian cancer." (PMID 38195844, 2024). "Our method proposed PCDH8 and BAZ2A as novel missense driver genes in ovarian carcinoma." (PMID 38195844, 2024).
autism (1 paper, 2021). Persistent deficits in social interaction and communication and interaction as well as a markedly restricted repertoire of activity and interest as well as repetitive patterns of behavior. "Furthermore, we identified ASD subgroup-specific hubs, for example, GAS5|SNORD76 and MTF2 for PDD-NOS or BAZ2A and MTCO2P12|COX2 for autism." (PMID 33719335, 2021).
cutaneous melanoma (1 paper, 2024). A primary melanoma arising from atypical melanocytes in the skin. "Cutaneous melanoma (SKCM) exhibited the highest frequency of BAZ2A gene alteration (> 10%)." (PMID 38433277, 2024).
endometrial carcinoma (1 paper, 2024). A malignant tumor arising from the epithelium that lines the cavity of the uterine body. "The survival analysis indicated that increased expression of BAZ2A was linked to a poor prognosis in patients with LIHC, KIRP, pheochromocytoma and paraganglioma (PCPG), and endometrial cancer (UCEC), while reduced expression of BAZ2A was linked to an adverse prognosis in KIRC." (PMID 38433277, 2024).
heart failure (1 paper, 2017). Inability of the heart to pump blood at an adequate rate to meet tissue metabolic requirements. "Bromodomain Adjacent to Zinc Finger Domain 2A (BAZ2A), plays an important role in the transcription deregulation in hypertrophy and heart failure." (PMID 28693530, 2017).
liver cancer (1 paper, 2024). An epithelial or non-epithelial malignant neoplasm that arises from the liver. "We collected tumor tissue samples from 80 patients with liver cancer and examined BAZ2A expression by immunohistochemistry." (PMID 38433277, 2024). "Our analysis revealed that BAZ2A exhibited elevated expression levels in tumor tissue from liver cancer patients in only 30 of 80 cases; this finding may be the small number of samples." (PMID 38433277, 2024). "Downregulation of BAZ2A inhibited proliferation, migration, and invasion and promoted apoptosis in LM6 liver cancer cell." (PMID 38433277, 2024).
metastatic prostate carcinoma (1 paper, 2024). A carcinoma that arises from the prostate gland and has spread to other anatomic sites. "Depletion of Baz2A has been studied in NIH3T3 and COS cells, where an increase in ribosome production and cell proliferation was observed, whereas in metastatic prostate cancer cell lines, Baz2A paradoxically contributes to cancer cell proliferation and viability." (PMID 38000389, 2024).
multiple myeloma (1 paper, 2009). "Three other genes were also down-regulated (SMARCA4, BAZ2A and SMARCC2): SMARCA4 is a drug target candidates in hyperdiploid multiple myeloma; BAZ2A is a novel nucleolar chromatin remodeling machine, and SMARCC2 was among the top discriminating genes in the good prognosis subgroup of MLL." (PMID 19761576, 2009).
Rett syndrome (1 paper, 2023). A severe neurodevelopmental disorder affecting the central nervous system.
tumor (14 papers, 2014 to 2025). "BAZ2A has been implicated in facilitating tumor cell proliferation, migration, and epithelial-mesenchymal transition (EMT), while exerting inhibitory effects on apoptosis in tumor cells." (PMID 38433277, 2024). "Apart from alterations in BAZ2A expression observed in cancer, we also found that the BAZ2A gene is mutated in variety of tumor types and BAZ2A protein also exhibited changes in phosphorylation levels." (PMID 38433277, 2024). "BAZ2A exhibited high expression levels in multiple tumor tissues and displayed a significant association with cancer patient prognosis." (PMID 38433277, 2024). "The Cancer Genome Atlas, Gene Expression Omnibus databases and TIMER2.0, cBioPortal and other tools were used to analyze the level of expression of BAZ2A in various tumor tissues and to examine the relationship between BAZ2A and survival, prognosis, mutation and immune invasion." (PMID 38433277, 2024). "miR-99a-5p downregulates BAZ2A, thereby disrupting normal epigenetic regulation, and activating tumor-promoting genes involved in tumor growth and mobility." (PMID 41294803, 2025). "BAZ2A, an epigenetic regulatory factor that affects ribosomal RNA transcription, has been shown to be highly expressed in several cancers and promotes tumor cell migration." (PMID 38433277, 2024). "Considering the crucial role of the tumor microenvironment on tumorigenesis and development, the effect of BAZ2A on immune cell infiltration was analyzed." (PMID 38433277, 2024). "This pattern is very similar to BAZ2A expression levels that previous work also detected to be high in metastatic PCa relative to normal tissue and localized tumours." (PMID 37184661, 2023). "Our findings demonstrated that BAZ2A expression may be related to Treg and macrophage cell infiltration in a variety of cancers and suggested that BAZ2A may participate in tumor development by interacting with a variety of immune cells." (PMID 38433277, 2024). "Our study suggests that BAZ2A functions as a promoter of cancer that may participate in cancer progression and promote tumor malignant behavior by regulating lipid metabolism." (PMID 38433277, 2024). "BAZ2A promotes the invasion of tumor cells and has cancer promoting activities." (PMID 38433277, 2024). "This suggests that the function of BAZ2A in cancer may be tumor-specific, and the mechanism by which it functions in different tumors may be complex, involving different signaling pathways and related molecules." (PMID 38433277, 2024). "Finally, our data also revealed that tumours expressing high BAZ2A levels also express high levels of KDM1A and TOP2A, suggesting common regulatory pathways." (PMID 37184661, 2023). "The distinct functional roles of BET and BAZ2A/B domains in TNBC suggests inhibition of their BD may result in selective tumor toxicities." (PMID 35672711, 2022). "Finally, in vivo assays validated that LINC00885 promoted tumor growth in CC and regulated miR-3150b-3p/BAZ2A axis." (PMID 35012615, 2022). "Importantly, 74% of these BAZ2A-TAM-dependent genes were significantly down-regulated by comparing BAZ2Ahigh/KDM1Ahigh tumours (i.e., 39 PCas that scored as the top 25% with the highest BAZ2A and KDM1A expressions, respectively) compared with BAZ2Alow/KDM1Alow tumours (41 PCas)." (PMID 37184661, 2023). "The S1395 site of BAZ2A showed higher phosphorylation levels in LIHC and KIRC tumor tissues in comparison to normal tissues, but lower phosphorylation levels in OV tumor tissues." (PMID 38433277, 2024). "The decrease in expression of SMARCA5 and BAZ2A that we also identified in this lineage may primarily be influencing chromosomal stability that is a characteristic of this tumor, nevertheless no change occurred after inhibition or transfection of the miRNA." (PMID 25493074, 2014).
tumor (continued). "However, the analysis of a large cohort of primary PCa and metastatic castration resistant PCa (CRPC) (333 and 118 tumours, respectively) revealed a significant positive correlation of both TOP2A and KDM1A levels with BAZ2A expression in both metastatic and primary tumors." (PMID 37184661, 2023).